C2 (complement C2)
Diseases named in the same sentence as C2 in open-access papers (continued):
Sharing a sentence is not in itself a finding about the gene and the disease.
viral infection (7 papers, 2016 to 2025). "In addition, C2 appeared to associate with positive regulation of inflammatory responses, as indicated by the high expression of Cd69 and the enrichment of IFN-γ signalling, toll-like receptor signalling and the pathways related to viral infections." (PMID 34858827, 2021). "AL2/C2 proteins from tomato mottle virus (ToMoV), tomato golden mosaic virus (TGMV), tomato yellow leaf curl virus (TYLCV), and BCTV are all phosphorylated by SnRK1 α, resulting in a delay in viral infection." (PMID 38400010, 2024). "The C2 protein of Tomato yellow leaf curl Sardinia virus (TYLCSV) interacts with CNS5 (a component of the COP9 signalosome) to disrupt the interaction between CUL1 and SCF ubiquitination activity, thereby suppressing JA biosynthesis for promoting viral infection." (PMID 41157791, 2025).
breast carcinoma (5 papers, 2018 to 2025). "mTORC1 and C2 complex activity and the antiproliferative effects of in vitro treatments were evaluated in ten human breast cancer cell lines which represent all breast cancer subtypes." (PMID 32899149, 2020). "Our findings have proposed C2 miR‐20a up‐regulation and C2 miR‐451 down‐regulation as early markers of chemo‐sensitivity in HR+/HER2− breast cancer." (PMID 30099860, 2018). "Finally, baseline miR‐222 overexpression (OR = 6.422, P = 0.049), C2 miR‐20a up‐regulation (OR = 0.144, P = 0.021) and C2 miR‐451 down‐regulation (OR = 8.213, P = 0.012) were predictive markers of response to NCT in HR+/HER2‐ breast cancer." (PMID 30099860, 2018).
leukemia (5 papers, 2014 to 2024). A malignant (clonal) hematologic disorder, involving hematopoietic stem cells and characterized by the presence of primitive or atypical myeloid or lymphoid cells in the bone marrow and the blood. "To further define the common transcriptional signature of MPAL, we performed unbiased single-cell gene set enrichment analysis (GSEA) on transcriptionally annotated leukemia cells systematically across all patients using all molecular signature database (MSigDB) hallmark and C2 gene sets 13,14." (PMID 39294124, 2024).
melanoma (5 papers, 2015 to 2025). A malignant, usually aggressive tumor composed of atypical, neoplastic melanocytes. "We identified immunoregulatory C2 IGFBP3+ melanoma cell subtypes in our investigation, and FOSL1 was a crucial transcription factor that aided in cell migration, proliferation, and survival." (PMID 41383633, 2025). "Through CellChat analysis, we further quantified the ligand-receptor interactions between endothelial cell subtypes and other cell types, highlighting the pivotal role of C2 GJA4+ endothelial cells in the melanoma microenvironment." (PMID 40639089, 2025). "Together, these findings demonstrate significant relationships between C2 gene expression level in melanoma biopsies and clinical outcomes following anti-PD1 treatment." (PMID 32117236, 2020). "In addition, CulPRIT gene subsets, such as the C2 gene signature, are predictive of immunotherapy response and survival of melanoma patients." (PMID 32117236, 2020).
preeclampsia (5 papers, 2014 to 2021). Preeclampsia is a hypertensive disorder of pregnancy that is characterized by new-onset hypertension with proteinuria presenting after 20 weeks of gestation, and depending on mild or severe forms may initially present with severe headache, visual disturbances, and hyperreflexia. "C1r expression is decreased in the implantation site of the preeclampsia model, and C2 deficiency results in thrombocytopenia during early pregnancy." (PMID 34827915, 2021). "Because inhibitory C2‐specific KIR2DL1 correlates with preeclampsia, whereas activating C2‐specific KIR2DS1 protects, this association pointed to KIR2DS5*006 being an activating C2‐specific receptor." (PMID 28685972, 2017). "This kind of balancing effect has been observed for KIR2DS1 and HLA-C2, where this combination of C2 and an activating receptor is associated with increased birth weight, while the combination of C2 and an inhibitory receptor is associated with low birth weight and increased risk of preeclampsia." (PMID 31138701, 2019). "Additionally, complement-associated genes were reduced in early-onset preeclampsia compared to healthy placentas (P=0.007), including complement 7 (C7), complement C1q A chain (C1QA), complement 2 (C2), and complement C1r (C1R)." (PMID 34992598, 2021).
diabetes (4 papers, 2020 to 2024). "In the combined analysis of genes unique to DR and those in common with diabetes mellitus at the threshold of <0.05, we identified C2, C4A, CD8A, HLA-DRB5, and HLA-DQA2, which have been associated with lymphocyte-mediated immunity (FDR 2.96 × 10−2)." (PMID 38791494, 2024). "Upregulation of both C2 and Factor B seen at baseline in T2D may be responsible for the well described increased levels of C3 and C3 activator in diabetes that are related to glucose intolerance and elevated fasting plasma glucose." (PMID 36643727, 2021). "The elevated complement C2 and Factor B at baseline in T2D subjects without any diabetes-related complications, and that remained consistently higher at all time points of the hypoglycemic challenge, are novel observations." (PMID 36643727, 2021). "While genome-wide studies have identified an association between type 2 diabetes mellitus (T2DM) and increased expression of a C2 calcium-dependent domain containing 4B (C2CD4B), no study has yet explored the possible direct effect of C2CD4B on vascular function." (PMID 38247525, 2024). "Moreover, we observed reduced plasma levels of zinc-α-2-glycoprotein, butyrylcholinesterase, and increased levels of complement C2 resembling findings in metabolic syndrome, diabetes and other non-communicable diseases." (PMID 32641735, 2020).
hepatocellular carcinoma (4 papers, 2005 to 2021). A malignant tumor that arises from hepatocytes. "Single nucleotide polymorphism (SNP) of complement component 2 (C2) has been found to be significantly associated with hepatocellular carcinoma (HCC)." (PMID 32626741, 2020). "Here, we examined the regulation of C2 complement expression in hepatoma cells infected in vitro with cell culture grown virus, and validated our observations using randomly selected chronically HCV infected patient liver biopsy specimens." (PMID 24983375, 2014). "Moreover, previous studies showed that the MHC genes share a common influence on HBV infection, liver cirrhosis, hepatocellular carcinoma as well as associate with different risk in these outcomes; i.e. HLA-DQ, STAT4, C2, HLA-DRB1 for liver cirrhosis and HCC, HLA-DQ for CHB." (PMID 33736632, 2021). "To study the regulation of the glucose-6-phosphatase promoter/luciferase reporter genes by C2/CREB, we decided to use the human hepatoma cell line HepG2, as it has been reported that activation of the cAMP signaling pathway stimulates glucose-6-phosphatase gene transcription in these cells." (PMID 15659240, 2005).
inborn error of immunity (4 papers, 2015 to 2025). A disorder in which the immune system is unable to mount an adequate immune response. "Among the top differing genes, we noted C2, a gene associated with primary immunodeficiencies (C2 deficiency; OMIM #217000)." (PMID 35562925, 2022).
malaria (4 papers, 2012 to 2025). Malaria is a serious and sometimes fatal disease caused by a parasite that commonly infects a certain type of mosquito which feeds on humans. "The initially increased mRNA expression of C1ra, C1s, and C2 in the liver of vaccinated mice suggests that protective vaccination accelerates the complex malaria-induced initial activation patterns of CP and LP." (PMID 40243929, 2025). "Similarly, we observed that C2 also targets both PKG and CDPK4 during P. berghei gametogenesis, further substantiating the dual specificity of C2 across the malaria lifecycle." (PMID 30315162, 2018). "A recent observation in keeping with this hypothesis is that the relatively weakly inhibitory combination of KIR2DL3 and C1 is a risk factor for cerebral malaria, and the activating combination of KIR2DS1 and C2 may be a risk factor for non-cerebral severe malaria." (PMID 27517293, 2016).
schizophrenia (4 papers, 2019 to 2024). A major psychotic disorder characterized by abnormalities in the perception or expression of reality. "The first study found a significantly increased activity for C2 (and C1, C1q, C3, C4) in schizophrenia patients compared to the healthy controls, whereas a second study found the C2 activity to be significantly lower in patients compared to the controls." (PMID 33670154, 2021). "We also probed the four complement genes located within the MHC region (i.e. C2, C4A, C4B and CFB) via schizophrenia PRS restricted to SNPs within each of them." (PMID 38649377, 2024). "The strongest genetic relationship for schizophrenia is with genetic markers located at the major histocompatibility complex (MHC) locus, which contains four genes that are related to the complement system (complement factor B, C2, C4A, and C4B)." (PMID 33670154, 2021). "It should also be admitted that among proteins significantly differed in quantitative measure, GPX3, IGKC, C2, and ATRN (adjusted p < 0.01) did not pass the significance level in the validation cohort of subjects with schizophrenia due to large deviation." (PMID 36747015, 2023).
Allergy (3 papers, 2020 to 2023). An allergy is an immune response or reaction to substances that are usually not harmful. "Besides, it can also suppress the activation of complement by inhibiting the C2 level in the classical complement pathway, hence interfering with the release of leukocytes and playing a dual role in preventing inflammation and allergy." (PMID 35035438, 2022). "C2, C9, IL5, SIGLEC15, and IL1RAP are examples of molecules with roles in immunity, inflammation and allergy that demonstrate seasonal effects." (PMID 33004787, 2020).
asthma (3 papers, 2020 to 2025). "Indirectly perturbed genes near ATF3 and EGR2 in the network include C2, SERPING1, ZG16B, and CEACAM3, all of which have been linked to immune response, asthma, or auto-immune diseases." (PMID 33095769, 2020).
colitis (3 papers, 2012 to 2022). Inflammation of the colon. "In fact, NFATc1 and c2 deficient mice display impaired Th1 and Th2 response, and NFATc2 deficiency has been reported to suppress colitis induced by oxazolone administration." (PMID 22479554, 2012). "The DSF c2-HDA represses invasion gene expression in a mouse colitis model." (PMID 32690633, 2020). "In the mouse colitis model, the DSF c2-HAD inhibited the expression of the virulence genes of intestinal pathogens and reduced the colonization of pathogenic bacteria in the intestine by interacting with transcription regulators of the AraC family." (PMID 35806111, 2022).
glaucoma (3 papers, 2023 to 2024). Increased pressure in the eyeball due to obstruction of the outflow of aqueous humor. "For each of the 4 clusters, notable genes associated with glaucoma, neuroinflammation, or reactive astrocytes were: Cluster 1 (Nrf2, Hspb1, S100β), Cluster 2 (Ptgs2, Clcf1), and Cluster 4 (C2, Tlr4, Lcn2, H2-T23, Thbs1, Il6ra)." (PMID 37759301, 2023).
lung carcinoma (3 papers, 2019 to 2024). "Intriguingly, tumours characterized by higher myeloid and endothelial C2 signature scores exhibited worse overall survival across multiple cancer types, including lung cancer (LC), PAAD, and STAD, as well as in the pan-cancer model." (PMID 39393173, 2024). "Furthermore, the C2 enrichment also indicated that these genes to be relevantly involved with poor survival statistics of lung cancer." (PMID 31323040, 2019). "In conclusion, this study identifies IFI30, RNH1 and CLEC3B, VCAN, IGFBP2, C2, TUBB4B as the proteins secreted by lung carcinoma cells and monocytes respectively as a result of their mutual interaction." (PMID 37784035, 2023). "In this study, we have demonstrated that the lung cancer cell-monocyte cross-talk modulates the secretion of IFI30, RNH1, CLEC3B, VCAN, IGFBP2, C2 and TUBB4B favoring tumor growth and metastasis." (PMID 37784035, 2023).
Myeloma (3 papers, 2018 to 2025). "C2 IGHG1+ Myeloma cells were enriched in cytoplasmic translation, ribosome biogenesis, ribonucleoprotein complex biogenesis, ribosomal small subunit biogenesis, rRNA processing, and ribosomal large subunit biogenesis." (PMID 40406148, 2025). "This analysis resulted in the identification of four distinct cell subsets: C0 IGLL5+ Myeloma Cells, C1 IGHG4+ Myeloma Cells, C2 MALAT1+ Myeloma Cells, and C3 IGHG1+ Myeloma Cells." (PMID 39281682, 2024). "The four identified cell subgroups were as follows: C0 IGLL5+ Myeloma Cells (724 cells), C1 IGHG4+ Myeloma Cells (310 cells), C2 MALAT1+ Myeloma Cells (305 cells), and C3 IGHG1+ Myeloma Cells (149 cells)." (PMID 39281682, 2024). "In the present study, we investigated the role of the mTORC1/C2 signaling pathway and AMPK activation the mechanism underlying the anti-myeloma using human MM cell lines in vitro and an in vivo xenograft mouse model." (PMID 29554968, 2018). "Thus, our results indicate that metformin inhibits myeloma cell growth by repressing mTORC1/C2 signaling pathway in an AMPK-dependent manner." (PMID 29554968, 2018). "Similarly, the molecular knockdown of AMPK abrogated metformin-induced inhibition of myeloma cell growth and attenuated metformin-induced repression of mTORC1/C2 signal pathway." (PMID 29554968, 2018).
pancreatic cancer (3 papers, 2015 to 2023). "There was no literature about the role of C2 in pancreatic cancer, but there was data showing C2 has a role in amplifying BCR signal transduction in each subpopulation of B-2 cells, but not B-1 cells." (PMID 37034706, 2023). "The in vitro and in vivo experiments further indicated the combination of AZD8055 and erlotinib synergistically inhibited the mTORC1/C2 signaling pathway, EGFR/AKT feedback activation, and cell growth, as well as suppressed the progression of pancreatic cancer in a xenograft model." (PMID 25654224, 2015).
pertussis (3 papers, 2019 to 2024). A contagious bacterial respiratory infection caused by Bordetella pertussis. "We previously showed that derivatives of the approved drug cyclosporine A (CsA) inhibit the intoxication of cells with C2 toxin and PT and reduce leukocytosis in an in vivo infection model of pertussis." (PMID 37505681, 2023).
Stroke (3 papers, 2010 to 2019). Sudden impairment of blood flow to a part of the brain due to occlusion or rupture of an artery to the brain. "Both C2 and Cfh are up-regulated after stroke together with other genes from this and other clusters." (PMID 26556046, 2015). "Maximum circulating concentration of complement components associated with the classical and lectin pathways of activation, C1q, C2 and C4b, and end stage mediators common to all pathways, C5 and C9, were increased in the first seven days after stroke in comparison to non-stroke controls." (PMID 31700615, 2019).
babesiosis (2 papers, 2023 to 2025). Babesiosis refers to a condition caused by microscopic parasites that infect the red blood cells. "Other identified proteins that differentiated uncomplicated from complicated babesiosis were various complement cascade components (CFI, CFP, C2, SERPING1, C8G), extracellular matrix components (TGFBI), acute phase proteins (ORM1, ITIH2, ITIH4, FGA, TF, RBP4) and lipoproteins (apoE)." (PMID 37353646, 2023).
colorectal cancer (2 papers, 2019 to 2025). A primary or metastatic malignant neoplasm that affects the colon or rectum. "In terms of tumors, the C2 gene has been associated with non-Hodgkin’s lymphoma (NHL) and colorectal cancer liver metastasis." (PMID 40002900, 2025).
dengue (2 papers, 2020 to 2024). "In conclusion, our study shows that MBL2 polymorphisms are associated with dengue in a Vietnamese study group and that C2, C4b, C5, C5a and factor D levels are significantly modulated in dengue patients and during the progression of dengue." (PMID 32913345, 2020). "Our data also indicate that the levels of C2, C4b, C5, C5a, C9, factor D and factor I are significantly associated with clinical parameters, especially with platelet counts, of dengue patients." (PMID 32913345, 2020). "The levels of C2, C5, and C5a were significantly higher in dengue and DWS patients compared to those in healthy controls (P < 0.0001) and also higher in DWS patients compared to those in dengue patients (P = 0.018, < 0.0001 and 0.049, respectively)." (PMID 32913345, 2020). "We measured the levels of MBL and the complement proteins C2, C4b, C5, C5a, C9, adipsin (factor D) and factor I in serum samples of dengue and DWS patients and healthy controls." (PMID 32913345, 2020). "C2, C5, and C5a levels were significantly increased in dengue patients compared to controls and are highest in DWS patients, indicating that the complement system is strongly activated in order to respond to DENV infection." (PMID 32913345, 2020). "In dengue patients, C2 levels correlated with the levels of C4b, C5, C5a and factor D (Spearman’s rho = 0.5, 0.39, 0.61, − 0.25; P < 0.0001, < 0.0001, < 0.0001 and = 0.0002, respectively)." (PMID 32913345, 2020).
endometriosis (2 papers, 2025). The growth of functional endometrial tissue in anatomic sites outside the uterine body. "From the Cancer Hallmarks perspective, GATA4, C2, MICB, and CLDN23 were implicated in evading immune destruction and tissue invasion, suggesting that even within intestinal tissues, relevant molecular signals associated with the pathophysiology of endometriosis may be present." (PMID 40863222, 2025).
glioma (2 papers, 2018 to 2022). A benign or malignant brain and spinal cord tumor that arises from glial cells (astrocytes, oligodendrocytes, ependymal cells). "High expression levels of proteins related to both mTORC1 and C2 activity were characteristic for the studied glioma cells, especially p-S6, p-4EBP1 and p-(Ser473)-Akt." (PMID 30574020, 2018). "In addition, NDRG1 is affected by not only the tumor microenvironment but also glioma treatments such as radiation, chemotherapeutic agents, and steroids, and its pathway is the mechanistic target of the rapamycin C2 (mTORC2)/SGK1 pathway." (PMID 35448004, 2022).
glomerulonephritis (2 papers, 2013 to 2025). A renal disorder characterized by damage in the glomeruli. "We describe a case of a post vaccine immune complex-mediated glomerulonephritis in an infant with compound heterozygous mutations of C2 complement component gene, which is the first such case in the literature." (PMID 24382852, 2013).
haemophilia A (2 papers, 2018 to 2022). "Structural analysis of C2 bound to BO2C11, a classical antibody inhibitor from a severe hemophilia A patient, supports the model of fVIII platelet association through residues M2199-F2200 and L2251-L2252 as they are completely sequestered in the BO2C11 paratope, potently blocking membrane binding." (PMID 36387287, 2022).
hereditary angioedema (2 papers, 2011 to 2023). Hereditary angioedema (HAE) is a genetic disease characterized by the occurrence of transitory and recurrent subcutaneous and/or submucosal edemas resulting in swelling and/or abdominal pain. "From the onset of these studies, in the late 1970s, I was of the opinion that bradykinin is the mediator of the swelling seen in hereditary angioedema and that C2 kinin might be an artifact." (PMID 23282402, 2011).
Hypoglycemia (2 papers, 2021 to 2022). A decreased concentration of glucose in the blood. "In the post-hypoglycemia follow up period, Complement C2 and Factor B remained elevated in T2D (Complement C2 at 4-h p < 0.05; Factor B at 30mins p < 0.001, 1-h p < 0.05 and 4-h p < 0.01)." (PMID 36643727, 2021). "For example, elevations in C2 indicate upregulation of the complement pathway in T2D, which could be a response to hypoglycemia." (PMID 36402758, 2022).